IL2 (interleukin 2)
Diseases named in the same sentence as IL2 in open-access papers (continued):
Sharing a sentence is not in itself a finding about the gene and the disease.
tumor (continued). "Th17 cells can stimulate CD8 + CTL response through IL-2 and pMHC I, and stimulate the expression of CCL2 and CCL20 in tumor microenvironment to promote the recruitment of various inflammatory leukocytes (DCs, CD4 + and CD8+ T cells)." (PMID 36874093, 2023). "This BsAb can robustly induce cytokines’ (IFN-γ, TNF-α, and IL-2) secretion in T cells and MUC1-expressing tumor cells’ co-culture assay." (PMID 37489369, 2023). "In order to characterize the in vitro cytotoxic properties of the CAR T cells obtained more comprehensively, the IL2 and IFNg levels in the supernatants of CAR T cells co-incubated with tumor cells for 12 h at a 1:2 ratio were measured by ELISA." (PMID 36835110, 2023). "We treated KP lung tumor–bearing mice with IL12-MSA, IL2-MSA, or the combination on days 7 and 14 of tumor growth and monitored mice for survival." (PMID 37669107, 2023). "IL-2 can induce the differentiation of natural killer cells (NK) and CTL and exert anti-tumor effects." (PMID 37256111, 2023). "Elevated expression of T cell activation markers CD25 and CD137, and the production of pro-inflammatory Th1 cytokines IL-2, TNF-α, and IFN-γ, at the tumor site were also consistent with heightened T cell activation when administered after carboplatin." (PMID 37660083, 2023). "We show that administration of naive CD4+ T cells polarized to Th2 cells, using IL-4, IL-2 and anti-IFN-γ antibody, not only prevented tumor growth, but reversed growth curve of colon and pancreas cell-derived allograft tumors." (PMID 36376448, 2023). "HF10 induces tumor necrosis, CD8+ cell infiltration, and the release of antitumor cytokines, including IL-2, IL-12, TNF-α, and IFN-α, -β, -γ, to inhibit tumor growth and prolong survival." (PMID 37958464, 2023). "IL-2 and IFN-γ were upregulated in the tumor microenvironment in the combination treated group, as were CD4 + T lymphocytes." (PMID 37253929, 2023). "Following tumor recognition, T cells showed increased expression of activation markers (CD137, CD69, IL-2, and TNF-α)." (PMID 37683639, 2023). "Slightly higher production of IL-2 and IFN-γ in mice treated with WT CD8+ T cells compared to control mice suggested impact of the tumor microenvironment on CD8+ T cells." (PMID 37415974, 2023). "Immunization with tumor cells, modified to secrete immune-augmenting cytokines such as IL-2, IFN-γ and GM-CSF, has resulted in the development of generalized MHC-restricted anti-tumor immune responses in animal models." (PMID 38002466, 2023). "Specifically, BBL-28.mζ CAR T-cells released higher levels of IFN-γ, IL-2, and GM-CSF at first and fourth stimulations with GL261 tumor cells (BBL-28.mζ vs other constructs p<0.05)." (PMID 37333156, 2023). "PBMCs were isolated from 11 UGI patients undergoing tumour resection on post-operative days (POD) 0, 1, 7 and 42 and expanded ex vivo using anti-CD3/28 and IL-2 for 5 days in the absence/presence of nivolumab or ipilimumab." (PMID 37359545, 2023). "Since the effector activity of T cells is also affected by the intratumoral environment, the levels of IL-2, IFN-γ and granzyme B (GZB) were measured by flow cytometry in spleen and tumor tissues on 21 and 28 daft." (PMID 37736849, 2023). "Meanwhile, T helper cells secrete various cytokines, including IL-2, TNF-⍺, and IL-12, which enhance natural killer cell-mediated immune responses to exert anti-tumor effects." (PMID 37874419, 2023). "GK-1 increased the levels of IL-2 and IFN-γ produced by tumor-related CD4+ and the levels of GZB and IFN-γ produced by tumor-related CD8+ T lymphocytes." (PMID 37736849, 2023). "On the other hand, PBRM-1-deficient tumors expressed increased cytokine pathway related genes such as IFN-γ, IL-2, IL-12, and CCL21, theoretically enhancing anti-tumor immunity." (PMID 37568390, 2023). "In BC, NK cells have been shown to reduce tumor growth in vivo and specifically kill CD44+CD24low/- BCSC from an HR+ cell line when activated with IL2 and IL15." (PMID 37445860, 2023).
tumor (continued). "In this study, the antitumour and antiangiogenic activity of a gene-electrotransfer combination of plasmids with transcripts for interleukins IL-2 and IL-12 was investigated in the CT26 mouse tumour model." (PMID 37629081, 2023). "This interaction also hampers the function of tumor-infiltrating CD4+/CD8+ T cells (CD4+/CD8+ TILs) and reduces the production of cytokines such as tumor necrosis factors, IFN-γ and Interleukin-2." (PMID 38003938, 2023). "Since 1990, cytokines responsible for conferring anti-tumor activity, interferon-α (IFN-α) and interleukin-2 (IL-2), have been used at high doses for the treatment in mccRCC." (PMID 37175653, 2023). "In the equilibrium phase, the immune system (mainly T helper type 1 (Th1) cells, cytotoxic T cells, and cytokines of type 1 immunity (IL12, IL2, interferon gamma (IFN-γ)) keeps tumor cells dormant or growing slowly." (PMID 37445860, 2023). "To test this notion, we inoculated mice with KP.SIY lung or flank tumors, treated tumor-bearing mice with IL2-MSA on day 6 of tumor growth, and analyzed the ability of SIY-reactive T cells to bind IL12-MSA ex vivo on day 7 of tumor growth." (PMID 37669107, 2023). "In PDAC xenograft immunodeficient mice, Ad-TNF-α-IL-2 boosted both CAR T-cell and host T-cell infiltration to the tumor site and changed host tumor immunological condition with M1 polarization of macrophages and augmented dendritic cell maturation." (PMID 37020537, 2023). "Interleukins, such as IL-2, IL-10, IL-12, IL15, and IL-21, and their receptors have been shown to be efficient mediators of anti-tumor immunity in preclinical cancer models." (PMID 37240247, 2023). "We studied the γc cytokines IL-2, IL-7, IL-15 and IL-21 or IFN-γ, as these cytokines have been shown to stimulate anti-tumor immunity." (PMID 37923822, 2023). "The primary role of IFN-γ is to restrict viral propagation and tumour progression, whereas TNF-α and IL-2 further induce functional maturation in NKC and promote the growth and development of other immune cells, yielding a more robust immune response." (PMID 37687141, 2023). "DC101 can decrease the high expression of VEGF after VDA therapy; temporarily normalize tumor blood vessels; increase the number of CD8+ T cells within the tumor; and significantly increase the levels of IFN-γ, TNF-α, and IL-2 after treatment." (PMID 37111692, 2023). "Tumor-immune phenotypes related to FOXA1 were studied by focusing on six immune-related pathways, including CD28 co-stimulation, IL2 signaling, cell recruitment, cytokine–cytokine receptor interaction, interferon signaling, and IL12 signaling." (PMID 37958805, 2023). "Systemic administration of IL2-MSA led to significantly increased ex vivo binding of fluorescently labeled IL12-MSA by SIY-reactive CD8+ T cells in both the lung and flank tumor setting." (PMID 37669107, 2023). "Further research is necessary to compare the molecular mechanisms underlying reconstituted immune networks, including CTL-NKT circuitry and anti-tumor activity, with those of CIK cells or αGalCer-pulsed IL-2/GM-CSF induced mixed immune cells." (PMID 37100864, 2023). "Increased secretion of interferon γ (IFN‐γ), interleukin (IL)‐2, and tumor necrosis factor α (TNF‐α) was measured in B7H3‐redirected BiTE‐T cells cocultured with B7H3‐positive tumor cells (A375, MV411, SKOV3, and THP‐1)." (PMID 36403209, 2023). "Cytokines, such as IL-2, IL-10, TGF-β and IFN, play a complex role in the regulation of immunity, which can promote or suppress anti-tumor immunity in different situations." (PMID 37398660, 2023). "Previously, a preclinical study using tumor-targeting IL2 treatment showed a tumor-infiltrating CD8+ T cell response and effective tumor control." (PMID 37835379, 2023). "The supernatant levels of IL‐2 and tumor necrosis factor‐α (TNF‐α) were significantly increased in OT‐I T cells cocultured with RA‐pretreated tumor cells." (PMID 36876644, 2023).
tumor (continued). "Cancer immunotherapy has risen rapidly since IL-2 was approved by FDA in 1991 for cancer immunotherapy, which significantly improved the prognosis of patients with multiple metastatic or refractory tumor in the following decades." (PMID 37692860, 2023). "Effector CD8+ T cells in the TME can produce IL-2, IL-12, and IFN-γ, and cytotoxicity improvement of CD8+ T cells can promote targeted killing of tumor cells." (PMID 37965271, 2023). "IL-2 with abrogated IL-2Rα (CD25) binding or enhanced IL-2Rβ binding was demonstrated to induce less efficient Treg expansion and tumor infiltration, with more efficient tumor-specific CD8+ T-cell proliferation." (PMID 36839658, 2023). "The final results showed that the combinational therapy of interleukin-2 and DOX-based TMC NPs have the potential to kill the tumor cells and enhanced the immune response against cancer." (PMID 38202616, 2023). "Moreover, they express effector molecules, which are destined to kill tumor cells, including perforin 1, granzyme B and TNFα, as well as multiple pro-inflammatory cytokines that are characteristic for activated macrophages and Th1 cells, including IL-1β, IL-6, IL-2 and IFNγ." (PMID 37174085, 2023). "The natural killer (NK) cells followed by IL-2 and IFN-γ were induced in mice model fed with fucoidan orally in tumour induced mice than the control mice." (PMID 37660108, 2023). "MDSCs, especially in the tumor microenvironment (TME), can result in NK cells exhaustion, by suppressing IL-2 mediated NK cell cytotoxicity, INF-γ production, and inhibiting NKG2D expression on NK cells." (PMID 36991390, 2023). "We found that tumor-specific CD8+ TILs produced more IFNγ; blood-derived tumor-specific CD8+ T cells produced more TNF and IL-2 after restimulation with PMA and ionomycin and contained more poly-functional (IFNγ/TNF/IL-2-coexpressing) cells." (PMID 37045833, 2023). "The pro-inflammatory cytokines and other soluble factors present in TME such as, IL-15, IL-2, IL-21, IFN-α, and GM-CSF further enhance the anti-tumor characteristic of DC." (PMID 36253762, 2022). "It induced more powerful antigen-specific immune responses, which were demonstrated by the prevention of tumor proliferation, a prolonged survival time and an ameliorative tumor microenvironment (increased levels of IFN-γ, IL-2 and CD8+ T lymphocytes)." (PMID 35002508, 2022). "In a murine model of GBM, the systemically injected IL-2/Hsp70-treated NK cells were able to efficiently cross the BBB and reach the tumor, establishing contact with the neoplastic cells." (PMID 35203609, 2022). "ELISA was used to investigate the effects of EPA on serum cytokine production, including TNF-α, IFN-γ, IL-2, AST, BUN, and IL-6, in H22 tumor-bearing mice." (PMID 35597811, 2022). "Mice treated with the OX40-modulating exosome exhibited increased frequencies of effector T cells with enhanced IL-2 and IFN-γ signaling and reduced Treg induction in both their tumour-draining LNs and their primary tumours." (PMID 36139665, 2022). "We found that both M-CSF- and IL-34-containing CARs enable T-cells to mediate selective destruction of tumour cells that express enforced or endogenous M-CSFR, accompanied by production of both IL-2 and interferon (IFN)-γ." (PMID 35883636, 2022). "The joint application of EGFRVIII-targeted CAR-T cells with Poly I: C prominently increased the tumor-killing ability of CAR-T cells against tumor cells and promoted the production and secretion of IFN γ and IL-2." (PMID 35935930, 2022). "Type 1 T helper cells, which release TNF-a, IL-2, and interferon-g (IFN-g), exert antitumor effects, while Type 2 T helper cells mainly produce IL-4 to suppress the host immune system and promote tumor growth." (PMID 36171881, 2022). "Among which, the expressions of anti-tumor cytokines including IL-2, IL-15 IL-17A, IFN-γ and TNF-α were up-regulated, while tumor-promoting cytokines including IL-4 and IL-10 were down-regulated in HER2.28ζ/PD-L1.BB CAR-T cells." (PMID 36402752, 2022).
tumor (continued). "IRE induced a change in the T helper 1/T helper 2 cell ratio towards T helper 1 dominance, an increase in macrophage tumor infiltration, and an increase in IFN-γ and IL-2 compared to controls." (PMID 35740542, 2022). "T lymphocytes mediate tumor immunity by secreting various cytokines into the TME, such as IL-2, IL-4, IL-5, IL17, IL-21, IL-22, and IFN-γ." (PMID 35464411, 2022). "We fused IL-2 to the 15 kD nanobody NJB2, previously shown to bind alternatively spliced extra-domain B (EIIIB) domain of fibronectin (FN-EIIIB), a tumor-specific glycoprotein, with nanomolar affinity." (PMID 35013154, 2022). "An ongoing phase I/II trial aimed at treating metastatic melanoma patients with tumour-infiltrating lymphocytes transduced with CXCR2, followed by high dose IL-2 has clinical outcome reports pending (NCT01740557)." (PMID 35205725, 2022). "Tumor infiltrating dendritic cells (DCs), and TGF-β, IL-2, and indoleamine-2, 3-dioxygenase-1 (IDO-1) are all essential cells and molecules that promote CD4+ T-cell differentiation into Tregs." (PMID 35371055, 2022). "Patients in the IRE group had elevated serum levels of immunogenic cytokines, including IL-2, IL-6, and TNF-α, which were related to anti-tumor immunity." (PMID 36428767, 2022). "We evaluated the ex vivo number of IL-2-, IL-6-, IL-10-, IL-12-, TNF-α- and IFN-γ-producing spleen cells, since tumor growth can be affected by cytokines." (PMID 35265317, 2022). "When cytokine production data were pooled for all six tumour cell lines, significantly greater IFN-γ and IL-2 production was observed for both 2G and 3G CARs in which M-CSF rather than IL-34 was used to confer specificity." (PMID 35883636, 2022). "Our work describes the use of Salmonella and Alb-IL2 as a novel approach to drive local inflammation in the TME and potent anti-tumor T cell responses." (PMID 35962391, 2022). "A further study by the same group was conducted in 2020, showing the in vitro secretion of RANTES and—when recognition of U87MG EGFRVIII+ tumor cells by CAR-NK cells occurred—a significant secretion of TNF-α, IFN-γ, IL-2, and IL-6 cytokines." (PMID 35203609, 2022). "Zinc enriches the microbiome in Prevotella, Proteobacteria and Actinobacteria and improves the function of the immune system by increasing the level of pro-inflammatory cytokines such as IL-1β, IL-2, IL-6, TNF-α and IFN-γ in the tumor environment." (PMID 36428677, 2022). "We found that RCE plus oxaliplatin apparently activates hPD-1 tumor-infiltrating CD8+ T cells, resulting in elevations of released interleukin-2 (IL-2) and granzyme B (GrB), and kills hPD-L1 MC38 CRC cells." (PMID 36139451, 2022). "When LCK activates T cells, the secretion of IL-2 increases, which, in turn, activates CD8+ T cells within the tumour to increase the ability of ICIs to inhibit tumours and reduce drug toxicity." (PMID 36291944, 2022). "CB CAR-T and PB CAR-T cells secreted higher levels of IL-2 and IFN-γ after coculture with Nalm6-GL tumor cells than PB (patient) CAR-T cells." (PMID 35965561, 2022). "Research found that Exos secreted from α-fetoprotein (AFP)-expressing DCs (DEXAFP) stimulated CD8+ T lymphocytes to express IFN-γ and secrete IL-2, which leaded to the reduced CD25+Foxp3+ Treg, IL-10 and TGF-β in the tumor microenvironment." (PMID 36733388, 2022). "This ICK demonstrated improved tolerability, pharmacokinetics and tumor targeting as well as preferential activation of CD8+ and NK immune effector cells over Tregs as compared with its wild-type IL-2-based counterpart." (PMID 36569901, 2022). "IL-4, IL-6 and IL-10 are abundantly expressed in TME and play more pro-tumor role, while IL-2, IL-12, IL-15 and IL-18, which are immunomodulatory or pro-inflammatory factors, are restricted in the TME and play more anti-tumor role." (PMID 36698392, 2022).
tumor (continued). "For further confirmation of our TME flow cytometry data showing CD4 and CD8 T-cell activation, we found an increase in Th1 pro-inflammatory cytokine (IFNγ, TNFα, IL-2, and KC/GRO) levels in the tumor lysate." (PMID 35651802, 2022). "The biological activity of GEN1046 on T cells was reflected by increases in IFNγ, TNFα, IL2, and CXCL10 in peripheral blood in MC38-hPD-L1 and MC38-WT tumor–bearing mice." (PMID 35176764, 2022). "To study tumor-specific CD4+ T-cell dysfunction, we measured the expression of exhaustion markers, as well as IFN-γ, TNF-α, and IL-2 production of recovered SMARTA cells." (PMID 35784297, 2022). "The treatment of tumor-bearing mice with glucomannan as a dietary supplement at the 4 mg dose increased the IFN-γ cytokine response, and at the 2 mg dose, it increased the IL-2 cytokine response." (PMID 36298611, 2022). "In the field of OS, a recent study combined an autologous tumor cell vaccine, ACT, and IL-2 together in dogs with OS and obtained remarkably prolonged survival compared to traditional amputation therapy." (PMID 35433427, 2022). "In lewis tumor-bearing mice, compared with the CON group, the concentrations of IL-2, TNF-α and INF-γ in the MOD group were decreased (P< 0.001)." (PMID 36389762, 2022). "In a poorly immunogenic melanoma mouse model, combination of non-IL-2 blocking anti-CD25 with Gvax vaccine induced tumor regression, delayed tumor progression and improved OS." (PMID 36058945, 2022). "Disruption of the IL-2 axis by engineering CAR T cells to express the IL-7 receptor would reduce the Tregs and improve anti-tumor response." (PMID 35617812, 2022). "In humans, Treg increment is related to worse outcomes in many tumor diseases, and the expansion of ICOS-positive Tregs is related to IL-2 therapy unresponsiveness." (PMID 36059465, 2022). "The group administered the cells and IL-2 weekly for three weeks, and results indicated that polyclonal CAR-γδ T cells can suppress tumor growth in this pre-clinical setting." (PMID 35740670, 2022). "Th1 activate anti-tumor immune reaction by secreting IL-2 and IFN-γ whereas Th2 suppress anti-tumor immune reaction by secreting IL-4, suppressing NK cells, and lowering tumor antigen expression." (PMID 36293435, 2022). "Consistent results were also obtained for the tumor-infiltrating CD3 and CD8 expression in these tumors as well as the amount of cytokines IL-2 and IFN-γ." (PMID 35296335, 2022). "In line with this, FACS analysis of expression of IL-2, IFNγ and TNF-α expression in T cells through intracellular staining revealed that combination therapy resulted in increased effector function of tumor-infiltrating CD8 + T cells." (PMID 36457047, 2022). "Saline-formulated mRNA for four cytokines gene (IL-2, IL-15, IFN-α, and GM-CSF) when administered at the tumor site led to systemic antigen-specific T cell expansion, granzyme B + T cell infiltration, and immunological memory development." (PMID 35189921, 2022). "IL-2 can promote the activation and proliferation of CD8+ T cells in the early stage of tumor, but it can switch its function to induce the exhaustion of CD8+ T cells in the late stage of tumor." (PMID 36119037, 2022). "When combined with adoptive transfer of ex-vivo gp100-stimulated Pmel-1 T cells, IL-2/NARA1 was more effective at expanding these TAA-specific T cells in tumor-draining lymph nodes and tumors compared to PBS- or recombinant human IL-2-treated mice." (PMID 35651800, 2022). "The efficacy of Lm-LLO-CD105A was associated with increased infiltration of polyfunctional (i.e, IFN-γ, TNF-α, and IL-2 producing) CD8+ and CD4+ T cells and reduction in immunosuppression within the TME, and reduced tumor vascularization." (PMID 36439126, 2022). "Engineering exosomes to express HSP-70, IL-2 and IL12 or surface anchorage of staphylococcus enterotoxin A (SEA) onto TDEs have also been shown to enhance the anti-tumor activity of NK cells." (PMID 35031075, 2022).